GLIPR1 (GLI pathogenesis related 1)
Diseases named in the same sentence as GLIPR1 in open-access papers (continued):
Sharing a sentence is not in itself a finding about the gene and the disease.
prostate carcinoma (continued). "Furthermore, given that GLIPR1 was shown to down-regulate MYC in prostate cancer, the relationship between GLIPR1 expression and MYC expression in MM PCs from newly diagnosed patients was also assessed in silico." (PMID 31995627, 2020). "Additionally, overexpression of GLIPR1 induced apoptosis of lung cancer cells and prostate cancer cells by activating reactive oxygen species/the JNK pathway, downregulating c-Myc, or suppressing AURKA and TPX2." (PMID 28771580, 2017). "In addition, it has been shown that in prostate cancer cells there is an inverse correlation between the expression of GLIPR1 and c-Myc, where restoration of GLIPR1 expression downregulates c-Myc and induces cell-cycle arrest." (PMID 26302043, 2015). "Increased expression of the GLIPR1 (Glioma-GLI pathogenesis-related 1) gene is associated with myelomocytic differentiation in macrophage, and decreased expression of this gene through gene methylation is found to be associated with prostate cancer." (PMID 26398136, 2015). "The aim of this study was to evaluate the hypothesis that the combination treatment with docetaxel and GLIPR1-ΔTM will synergistically induce greater cell death and inhibit the emergence of resistance and development of metastatic potential in prostate cancer (PCa) cells." (PMID 26084402, 2015). "It has been shown that the human glioma pathogenesis-related protein 1 (GLIPR1), a PR1 homologous gene, has tumor suppressor activities and is involved in the restoration of function in prostate cancer cells." (PMID 32629961, 2020). "GLI pathogenesis-related 1 (GLIPR1) was originally identified in glioblastomas and its expression was also found to be down-regulated in prostate cancer." (PMID 26988096, 2016). "We found that GLIPR1 inhibited expression of ERBB2/3 and proliferation of both lung cancer (A549, PC14) and prostate cancer (LNCaP) cells." (PMID 26988096, 2016). "GLIPR1, or GLI pathogenesis related 1, has proapoptotic activity in prostate cancer cells, is expressed at high levels in the testes and may have a role in sperm-oocyte interactions." (PMID 28068351, 2017). "Although GLIPR1 has been reported to possess tumor suppressor activities in prostate cancer cells, its function in lung cancer have not yet been reported." (PMID 26988096, 2016). "The aim of the current study was to analyze the involvement of methyl-CpG binding proteins (MBDs) and histone modifications on the regulation of CD44, Cyclin D2, GLIPR1 and PTEN in different cellular contexts such as the prostate cancer cells DU145 and LNCaP, and the breast cancer cells MCF-7." (PMID 20565761, 2010).
glioblastoma (12 papers, 2010 to 2022). The most malignant astrocytic tumor (WHO grade IV). "In contrast, in other tumor types such as glioblastoma, GLIPR1 over-expression is associated with an increase in cellular proliferation and tumor invasion." (PMID 26302043, 2015). "First experiments in nude mice (NMRI:nu/nu) explored effects of stringent doxycycline-dependent GliPR1 knockdown on glioblastoma tumor growth, using U87-MG clone 980-5 transduced with GliPR1 sh#301." (PMID 33856615, 2021). "We first transduced the U87-MG human glioblastoma cell line with GliPR1 shRNAs (shGliPR1s) using a lentiviral “all-in-one” TetOn-shRNA vector, which produces stringent doxycycline-dependent knockdown." (PMID 33856615, 2021). "It is unclear why GliPR1 manifests the apparent paradox that in glioblastoma and some tumors it is overexpressed and appears to be an oncoprotein yet in other tumors it has downregulated expression and appears to be a tumor suppressor." (PMID 33856615, 2021). "Experiments used human glioblastoma cell lines transduced with GliPR1 shRNA (sh#301, sh#258)." (PMID 33856615, 2021). "No clinical study so far has evaluated inhibition of GliPR1 overexpression as a therapeutic strategy in glioblastomas." (PMID 33856615, 2021).
lung carcinoma (10 papers, 2016 to 2025). "GLI pathogenesis-related 1 functions as a tumor suppressor in lung cancer, and during lung tumorigenesis, the expression of GLIPR1L2 is downregulated." (PMID 38791918, 2024). "GLIPR1 promotes an increase in Bcl-2 expression to subsequently decrease the apoptosis of A549/DDP lung cancer cells." (PMID 34142021, 2021). "Overexpression of GLIPR1 in prostate, bladder and lung cancer, as well as osteosarcoma cells, has been demonstrated to reduce tumour cell proliferation and/or colony formation in vitro." (PMID 31995627, 2020). "Ectopic expression of ERBB3 partially restores growth inhibition induced by GLIPR1, suggesting that GLIPR1 inhibits lung cancer cell growth through suppressing ERBB3." (PMID 26988096, 2016). "This study reveals a novel pathway that PRMT5/WDR77 regulates GLIPR1 expression to control lung cancer cell growth and GLIPR1 as a potential therapeutic agent for lung cancer." (PMID 26988096, 2016). "The consequence of GLIPR1 on growth of lung cancer cells in the tissue culture and lung tumor xenografts in the nude mice was observed." (PMID 26988096, 2016). "Expression of GLIPR1 was down-regulated during lung tumorigenesis and its expression suppressed growth of lung cancer cells in the tissue culture and lung tumor xenografts in mice." (PMID 26988096, 2016). "GLIPR1 expression was down-regulated during lung tumorigenesis and re-expression of GLIPR1 inhibited proliferation of lung cancer cells and growth of lung tumor xenografts." (PMID 26988096, 2016). "GLIPR1 regulates lung cancer growth through the V-Erb-B avian erythroblastic leukemia viral oncogene homolog 3 (ErbB3)." (PMID 26988096, 2016). "Additionally, miR-301a inhibits the Fra-2/GLIPR1 (GLI pathogenesis-related 1) axis to increase cisplatin resistance in lung cancer." (PMID 40821785, 2025). "Overexpression of GLIPR1 induces apoptosis in prostate and lung cancer cells." (PMID 34142021, 2021). "GLIPR1 has been extensively studied in various cancers, including prostate, astrocytic, wilms, acute myeloid leukemia, melanoma, and lung cancers." (PMID 28771580, 2017). "The expression of GLIPR1 was reduced in prostate and lung cancer cells compared to normal cells." (PMID 28771580, 2017). "GLIPR1 has been found to be expressed at high levels in astrocytic, wilms, acute myeloid leukemia, and melanoma cancers and at low levels in prostate, and lung cancer." (PMID 28771580, 2017). "GLIPR1 expression was also analyzed in the TCGA lung cancer cohort." (PMID 26988096, 2016). "A few of the top target genes, such as MT1G and GLIPR1 were, in fact, common targets of both miR-1246 and miR-1290, thus suggesting that they may play an important role in mediating the function of lung cancer cells." (PMID 27325363, 2016). "This study identifies GLIPR1 as a tumor suppressor for lung cancers." (PMID 26988096, 2016). "Moreover, ERBB3 expression is inversely correlated with GLIPR1 in 230 lung cancers." (PMID 26988096, 2016). "Thus, GLIPR1 may serve as a novel therapeutic agent for lung cancer by using either gene or protein delivery methods." (PMID 26988096, 2016). "In searching for genes that mediate PRMT5 and WDR77 functions in lung cancer cells, we performed DNA microarray analysis (GSE56757) with lung adenocarcinoma A549 cells expressing WDR77 or PRMT5 shRNA and found that the loss of WDR77 or PRMT5 expression significantly up-regulated GLIPR1 expression." (PMID 26988096, 2016). "In contrast, lung cancer samples express high levels of PRMT5, WDR77, ErbB2, ErbB3 and FGFR3 and decreased levels of GLIPR1, Leprel1 and BTG2." (PMID 27480244, 2016).
melanoma (9 papers, 2013 to 2024). A malignant, usually aggressive tumor composed of atypical, neoplastic melanocytes. "Glipr1, which encodes glioma pathogenesis-related protein-1, has been linked to macrophage differentiation, and the invasive potential of melanoma cells." (PMID 25674539, 2015). "Increased GLIPR1 transcript levels were also associated with increased invasion in an independent set of publically available microarray data generated from melanoma cell lines with experimentally validated invasive potential." (PMID 24010123, 2013). "Variable GLIPR1 transcript levels were associated with differences in promoter methylation in a panel of melanoma cell lines of known invasive potential, with increasing promoter methylation associated with decreasing GLIPR1 abundance (r2 = 0.82, p = 0.037)." (PMID 24010123, 2013). "Based on our GLIPR1 promoter methylation data, we speculate that perhaps genome-wide epigenetic re-programing can occur in melanoma cells, to which GLIPR1 is sensitive, and that is associated with phenotype switching mechanisms in melanoma cells." (PMID 24010123, 2013). "In contrast, GLIPR1 is overexpressed in astrocytic, wilms, acute myeloid leukemia, and melanoma cancers." (PMID 28771580, 2017). "Immunohistochemical studies of melanoma tissue microarrays showed moderate to high staining for GLIPR1 in 50% of specimens analyzed." (PMID 24010123, 2013). "Immunohistochemical staining of melanoma tissues confirmed variable expression of GLIPR1, similar to that observed in NZM cell lines, with almost an equal proportion of melanoma specimens expressing relatively higher or relatively lower levels of GLIPR1." (PMID 24010123, 2013). "We analyzed GLIPR1 levels in the study of metastatic melanoma samples by Bogunovic and colleagues, which includes clinical data, and found that elevated GLIPR1 levels were significantly positively correlated with survival." (PMID 24010123, 2013). "Overall, the results of our Transwell assays and knockdown experiments support the notion that GLIPR1 is involved in mediating the invasive potential of melanoma cell lines." (PMID 24010123, 2013). "Of the 76 melanoma specimens analyzed, 50% showed moderate to high immuno-reactivity (++ and +++) for GLIPR1." (PMID 24010123, 2013). "We also show that GLIPR1 is variably expressed in melanoma tissue samples, and can be detected in certain adnexal structures of normal epidermis." (PMID 24010123, 2013). "Immunohistochemical staining of malignant melanoma tissue samples showed variable expression of GLIPR1 in a similar fashion to the NZM cell lines." (PMID 24010123, 2013). "We identified GLIPR1 as part of a gene expression signature that predicted invasive potential in melanoma cell lines." (PMID 24010123, 2013). "GLIPR1 was variably expressed in metastatic melanoma cells, and transcript levels correlated with degree of GLIPR1 promoter methylation in vitro." (PMID 24010123, 2013). "Having demonstrated a relationship between GLIPR1 expression and migration/invasion in melanoma cell lines, we investigated GLIPR1 expression in melanoma and skin tissue samples." (PMID 24010123, 2013). "A survey of publically available array data shows that GLIPR1 levels are variable in melanoma, which is in agreement with our observations in this study." (PMID 24010123, 2013). "Here we report on the role of GLIPR1 in melanoma in more detail, and confirm that GLIPR1 is variably expressed in melanoma cells, which is underpinned by differential promoter methylation, and that GLIPR1 levels correlated with invasive potential." (PMID 24010123, 2013). "High expression of GLIPR1 increased proliferation of breast cancer and invasion of melanoma." (PMID 38368374, 2024). "However, there is little useful published melanoma array data that includes patient information to determine if GLIPR1 transcript abundance is correlated with clinical outcome." (PMID 24010123, 2013). "Here we investigated GLIPR1 expression in metastatic melanoma cell lines and tissue." (PMID 24010123, 2013).
melanoma (continued). "siRNA-mediated knockdown of GLIPR1 inhibited migration and invasion in melanoma cell lines." (PMID 24010123, 2013). "It does not appear that GLIPR1 levels are uniformly elevated with increasing melanoma stage, which is again consistent with GLIPR1 being sensitive to dynamic gene expression changes that are associated with the postulated phenotype switching capacity of melanoma cells during disease progression." (PMID 24010123, 2013). "We have previously demonstrated that endogenous GLIPR1 activates JNK signaling and docetaxel was also found to induce JNK signaling and subsequent apoptosis in melanoma cells." (PMID 26084402, 2015). "Among the five melanoma cell lines, NZM15 cells had the lowest level of GLIPR1 expression and was used as the baseline reference." (PMID 24010123, 2013). "Whether GLIPR1 promoter methylation is dynamic during disease progression or shows higher or lower levels of methylation in metastatic melanoma cells compared to normal melanocytes, benign nevi and primary melanoma remains unknown and requires further investigation." (PMID 24010123, 2013). "Although we demonstrated variable GLIPR1 staining in melanoma tissue microarray samples, these samples lacked clinical information, so the clinical significance of variable GLIPR1 expression remains unknown." (PMID 24010123, 2013). "However, GLIPR1 expression analysis in melanoma has not been previously reported." (PMID 24010123, 2013).
bladder cancer (6 papers, 2015 to 2024). "Apoptosis induction upon GLIPR1 overexpression in a tet-on stable clone of bladder carcinoma cell line was reported to be dependent on the production of ROS." (PMID 26302043, 2015). "GLIPR1 plays a pro-apoptotic role in prostate and bladder cancer cells." (PMID 26302043, 2015).
astrocytic tumor (5 papers, 2013 to 2015). A glial tumor of the brain or spinal cord showing astrocytic differentiation. "We previously reported that GLIPR1/RTVP-1 acts as tumor promoter in GBM and that its expression is increased in astrocytic tumors, in a grade-dependent manner." (PMID 26267319, 2015).
breast carcinoma (4 papers, 2010 to 2024). "The highest inductions were for GLIPR1 (~30-fold), a gene hormonally-regulated in breast cancer cells, and SYTL2 (~12-fold), a trafficking protein also known as Breast Cancer-Associated antigen SGA-72M." (PMID 27351228, 2016). "The identified DEGs, which were involved in cell cycle, including CDC20, BUB1, GLIPR1, MCM2, and CCNB1, could have a crucial function in the development of breast cancer, and may become potential targets or prognostic markers for breast cancer." (PMID 25385471, 2015).
Wilms tumor (4 papers, 2013 to 2024). An embryonal neoplasm characterized by the presence of epithelial, mesenchymal, and blastema components. "More recently, GLIPR1 was shown to be differentially expressed in other cancers including ovarian, acute myeloid leukemia, and Wilms’ tumor." (PMID 24010123, 2013). "The overexpression of GLIPR1 is known in Wilms tumors and occurs with a frequency of 67%." (PMID 27043538, 2016). "Downregulation of the miR-30 family in Wilms tumors might provide a further mechanism for Wilms tumors to increase GLIPR1 protein expression besides the increased transcription due to promoter hypomethylation." (PMID 27043538, 2016). "In addition, methylation studies of GLIPR1 showed significant hypomethylation in Wilms’ tumor relative to normal tissue." (PMID 24010123, 2013).
acute myeloid leukemia (3 papers, 2013 to 2017). Acute myeloid leukemia (AML) is a group of neoplasms arising from precursor cells committed to the myeloid cell-line differentiation. "More recently, GLIPR1 has been found to be differentially expressed in ovarian cancer and acute myeloid leukemia." (PMID 24010123, 2013).
ovarian carcinoma (3 papers, 2013 to 2019). A malignant neoplasm originating from the surface ovarian epithelium. "Interestingly, Ddr2, Ereg, Glipr1, Calcr, and Ankrd1, all up-regulated in STOSE cells, have been shown to be up-regulated in primary tumors and ovarian cancer cells." (PMID 24672774, 2014).
leukemia (2 papers, 2014 to 2021). A malignant (clonal) hematologic disorder, involving hematopoietic stem cells and characterized by the presence of primitive or atypical myeloid or lymphoid cells in the bone marrow and the blood. "The meta-analysis showed a significant heterogeneity (I2 = 83%) among these studies, and revealed that GLIPR1 hypermethylation was associated with the increased risk of leukemia (P = 0.0002, OR = 5.96, 95% CI = 2.29–15.46)." (PMID 24810788, 2014). "Our analysis also demonstrated that DNA methylation of GLIPR1 gene was a risk factor for leukemia." (PMID 24810788, 2014). "Meta-analysis between GLIPR1 methylation and leukemia was involved with 6 case-control studies among 384 controls and 309 cases." (PMID 24810788, 2014).